CLCF1 (cardiotrophin like cytokine factor 1)
Description:
Functions as a cytokine, either alone or by forming a stable complex with soluble CRLF1 or CNTFR. Binds to CNTFR complex (CNTFR, IL6ST/gp130, LIFR) or can signal via trans-signaling using soluble CNTFR subunits. Mechanistically, ligand binding to CNTFR, induces dimerization of the IL6ST/gp130 and LIFR, which activates JAK tyrosine kinases (JAK1 or JAK2 and to lesser extent TYK2) bound to their intracellular domains. These kinases subsequently phosphorylate IL6ST/gp130 and LIFR. The tyrosine phosphorylated signaling receptors serve in turn as docking sites for recruitment and activation of signal transducer and activators of transcription (STAT3 and to lesser extent STAT1). Moreover, CLCF1/CLF heterodimer induces tyrosine phosphorylation of PTPN11, that associates with IL6ST/gp130-LIFR, which in turn recruits PIK3 protein kinase followed by AKT protein phosphorylation. Participates in the survival of embryonic motor neurons. Also stimulates B-cells (By similarity).
Synonyms: BSF-3; NNT-1; BSF3; CLC; NNT1; NR6; CISS2
Tractability: Antibody: its Gene Ontology location is reachable by antibodies, with high confidence; UniProt places it where antibodies can reach, with medium confidence; UniProt predicts a signal peptide or a membrane-spanning region.
Gene: Protein-coding gene on chromosome 11 (67,364,168 to 67,374,177, reverse strand). Ensembl gene ENSG00000175505.
Subcellular location: Secreted
Subcellular location (Human Protein Atlas): Nuclear bodies; Vesicles; Predicted to be secreted
Pathways (Reactome):
Immune System: IL-6-type cytokine receptor ligand interactions
Gene Ontology:
Molecular function: ciliary neurotrophic factor receptor binding; cytokine activity; protein binding; signaling receptor binding; growth factor activity
Biological process: cell surface receptor signaling pathway via JAK-STAT; cell surface receptor signaling pathway via STAT; cytokine-mediated signaling pathway; negative regulation of neuron apoptotic process; positive regulation of cell population proliferation; B cell differentiation; cell surface receptor signaling pathway; positive regulation of astrocyte differentiation; positive regulation of B cell proliferation; positive regulation of immunoglobulin production; positive regulation of isotype switching to IgE isotypes
Cellular component: CNTFR-CLCF1 complex; CRLF-CLCF1 complex; extracellular region
Genetic constraint (gnomAD): Loss-of-function variants: 8 observed, 19.67 expected, observed/expected ratio (o/e) 0.41, 90% interval 0.24 to 0.73. The upper end of that interval is the gene's LOEUF score, 0.73, which puts it in group 3 of 6, group 1 being the genes least tolerant of losing a copy. Missense variants: 233 observed, 300.7 expected, observed/expected ratio (o/e) 0.77, 90% interval 0.69 to 0.86. Synonymous variants: 111 observed, 125.42 expected, observed/expected ratio (o/e) 0.89, 90% interval 0.76 to 1.04.
Homologues: Orthologues: chimpanzee CLCF1 (100% identical), dog CLCF1 (98% identical), mouse Clcf1 (97% identical), rat Clcf1 (97% identical), pig CLCF1 (96% identical), rabbit CLCF1 (96% identical), guinea pig CLCF1 (95% identical), tropical clawed frog clcf1 (59% identical), zebrafish clcf1 (41% identical). Paralogues in human: CTF1 (19% identical).
Diseases named in the same sentence as CLCF1 in open-access papers:
CLCF1 is named in the same sentence as 48 diseases in open-access papers, as found by Europe PMC text mining. Sharing a sentence is not in itself a finding about the gene and the disease. The quoted sentences say what the papers report.
hepatocellular carcinoma (6 papers, 2021 to 2025). A malignant tumor that arises from hepatocytes. "Cardiotrophin-like cytokine factor 1 (CLCF1) derived from CAFs induces N2 neutrophil polarization to facilitate hepatocellular carcinoma (HCC) progression." (PMID 36032075, 2022). "In hepatocellular carcinoma (HCC), CLCF1 enhances CXCL6 and TGF-β expression through the Akt/ERK1/2-STAT3 pathway, promoting stem cell traits and self-renewal in cancer cells." (PMID 40969371, 2025). "As a recent study of hepatocellular carcinoma reported, CAF-derived cardiotrophin-like cytokine factor 1 (CLCF1) induces the polarization of N2-phenotype neutrophils by upregulating CXCL6 and TGF-β expression in tumor cells, thereby facilitating tumor progression." (PMID 34635121, 2021).
cold-induced sweating syndrome (5 papers, 2013 to 2023). Cold-induced sweating syndrome (CISS) is characterized by profuse sweating (involving the chest, face, arms and trunk) induced by cold ambient temperature. "Crisponi syndrome is now considered to be the same disorder as cold-induced sweating syndrome, and cold-induced sweating syndrome is caused by mutations in the CLCF-1 or CRLF-1 genes." (PMID 24618404, 2014). "Mutation in the cytokine receptor-like factor 1 and the cardiotrophin-like cytokine (CRLF1 or CLCF1 genes) phenotypically presents as cold induced sweating syndrome (CISS), which is a rare autosomal recessive disorder." (PMID 24073352, 2013). "The deficiency of CLCF1 function causes cold-induced sweating syndrome (CISS), a disease associated with respiratory and neural developmental defects." (PMID 35265072, 2022). "Mutations in CRLF1 or CLCF1 are associated with Crisponi/cold-induced sweating syndrome (CS/CISS)." (PMID 35055176, 2022).
focal segmental glomerulosclerosis (4 papers, 2015 to 2022). A renal disorder characterized by sclerotic lesions in the glomeruli. "CLCF1 and others have been identified as potential circulating permeability factors in the plasma of patients with focal segmental glomerulosclerosis (FSGS), a clinicopathological syndrome characterized by nephrotic-range proteinuria with a high incidence of progression to end-stage renal disease." (PMID 35055176, 2022). "We have identified CLCF-1 as a potential injurious factor in the human renal disease focal segmental glomerulosclerosis (FSGS)." (PMID 26146641, 2015).
lung carcinoma (4 papers, 2022 to 2025). "Interestedly, the CLCF1–CNTFR axis played an important pro-oncogenic role in lung cancer, and its inhibition exhibited significant therapeutic effects." (PMID 36034849, 2022). "In lung cancer, CLCF1 is also a critical protumorigenic factor for CAFs, and an engineered decoy receptor targeting CLCF1-CNTFR signaling was confirmed to induce anti-tumor activity in lung adenocarcinoma." (PMID 35265072, 2022). "Notably, these results converge with those of recent work indicating a role for the CLCF1–CNTFR signalling axis in lung cancer." (PMID 40673604, 2025).
glioma (3 papers, 2021 to 2023). A benign or malignant brain and spinal cord tumor that arises from glial cells (astrocytes, oligodendrocytes, ependymal cells). "The results suggested that the expression of CLCF1 was an independent prognostic factor among the relevant clinical features of glioma and possessed the potential to be a target associated with response to immunotherapy." (PMID 35265072, 2022). "The biological function analysis of CLCF1 in glioma showed that CLCF1 was closely associated with immune signatures, including immune-related pathways, immune cell infiltration, and immune checkpoints." (PMID 35265072, 2022). "We comprehensively analyzed the correlation between CLCF1 expression, prognosis, clinicopathological features, tumor mutations, and tumor immunity based on publicly available datasets of clinically characterized glioma patients." (PMID 35265072, 2022). "On univariate Cox analysis, the WHO grade, age, IDH mutation status, 1p/19q deletion status, MGMT promoter methylation status, and CLCF1 expression were closely related to the prognosis of glioma in TCGA and CGGA datasets." (PMID 35265072, 2022). "CLCF1 expression is an independent prognosticator and a promising therapeutic target correlated with immunotherapy in glioma." (PMID 35265072, 2022). "We found that the mRNA and protein expression of CLCF1 were the lowest in normal tissues and increased with grade in glioma samples." (PMID 35265072, 2022). "To explore the potential role of CLCF1 in the occurrence and development of pan-glioma, we performed GSVA using the TCGA and CGGA datasets." (PMID 35265072, 2022). "Elevated CLCF1 expression was common in cancers and usually predicted poor prognosis, which was also consistent with gliomas." (PMID 35265072, 2022). "In the present study, we identified the prognostic significance of CLCF1 in gliomas based on RNA-sequencing data and clinical data of glioma patients extracted from The Cancer Genome Atlas (TCGA) and the Chinese Glioma Genome Atlas (CGGA)." (PMID 35265072, 2022). "In conclusion, this study demonstrates that CLCF1 has extensive prognostic significance in gliomas, and its overexpression correlates with immunosuppression and poor prognosis." (PMID 35265072, 2022). "The results indicated that CLCF1 achieved broader and more reliable prognostic ability than IL-6 in gliomas." (PMID 35265072, 2022). "To further confirm the differences in expression of CLCF1 in glioma and normal brain tissues, we used WB and qRT-PCR to detect protein and gene expression transcription levels in the samples." (PMID 35265072, 2022). "To further assess the prognostic value of CLCF1 in glioma, we grouped patients into high and low CLCF1 expression subgroups to conduct KM survival analysis." (PMID 35265072, 2022). "In the multivariate Cox proportional hazard model, the expression of CLCF1 was an independent prognostic factor in gliomas." (PMID 35265072, 2022). "The expression of CLCF1, AEBP1, and OS9 is significantly associated with the prognosis of PTEN-wt glioma, indeed which are significantly different between high-risk score patients and low-risk patients in the PTEN-mut subgroup (p < 0.001)." (PMID 34336645, 2021). "Due to the higher malignancy of the PTEN-mut glioma, we look for potential therapies targeting the prognostic signatures (CLCF1, AEBP1, and OS9) in this subgroup." (PMID 34336645, 2021). "Similar enrichment analysis results were also seen in independent analyses of LGG and GBM, suggesting that CLCF1 may be involved in all grades of glioma and played a similar role in promoting cancer." (PMID 35265072, 2022).
glioma (continued). "Moreover, glioma patients with low CLCF1 expression showed a greater tendency to respond to anti-PD1/PD-L1 immunotherapy, indicating CLCF1 also had potential clinical significance in guiding immunotherapy." (PMID 35265072, 2022). "Based on The Cancer Genome Atlas (TCGA), we conducted a bioinformatics analysis to investigate the clinical significance and biological functions of CLCF1 in glioma at the transcriptional level and predicted the response to immunotherapy of glioma patients with different CLCF1 expression levels." (PMID 35265072, 2022). "Similar results also exist when the comparison was executed in the separated LGG and GBM datasets, which indicated that CLCF1 may played a stable role in the immune process of glioma." (PMID 35265072, 2022). "Inhibition of CLCF1 to reduce phosphorylation of STAT3 may be an effective strategy for treating glioma with mutant PTEN." (PMID 34336645, 2021). "And CLCF1 as a member of the IL6 family had a better predictive value for prognosis and immunotherapy response in glioma than that of IL6 and other IL6 family members." (PMID 35265072, 2022). "In our study, CLCF1 not only showed more accurate and broader prognostic predictive ability than other IL6 family members in the gliomas data cohort but also had better sensitivity to anti-PD-L1 treatment than other family members." (PMID 35265072, 2022). "Due to the higher malignancy of the PTEN-mut gliomas, we explored the independent prognostic signatures (CLCF1, AEBP1, and OS9) for a potential therapeutic target in PTEN-mut glioma." (PMID 34336645, 2021). "Our study further confirms the importance and potential therapeutic intervention implications of CLCF1 and AEBP1 in PTEN mutant glioma." (PMID 34336645, 2021). "Cardiotrophin-like cytokine factor 1 (CLCF1) has been described as an oncogene and a potential therapeutic target in a variety of cancers, but its role in glioma remains unknown." (PMID 35265072, 2022). "Thus, in the PTEN-mut glioma, CLCF1, AEBP1, and OS9, which are significantly associated with survival time, may induce glioma progression and are critical targets for diagnosis, prognosis prediction, and treatment, giving therapeutic recommendations to glioma with mutant PTEN." (PMID 34336645, 2021). "Therefore, (+)-JQ1 potentially competes for and binds to the CLCF1, AEBP1, and OS9 proteins, resulting in the interruption of the pro-oncogenic pathway in PTNE-mut gliomas." (PMID 34336645, 2021). "In the PPI network of CLCF1, the signal transducer and activator of transcription 3 (STAT3) is upregulated in PTEN-mut but not in the PTEN-wt subgroup (PTEN-mut vs. Normal, PTEN-wt vs. Normal), showing STAT3 is correlated with PTEN-mut glioma." (PMID 34336645, 2021). "To verify that previous identified prognostic genes of TCGA-glioma PTEN-mut are also the prognostic genes in IDH1-wt patients with PTEN-mut, we observed that AEBP1, CLCF1, and OS9 were significantly prognostic genes in IDH1-wt, IDH1-wt/GBM, or IDH-wt/LGG gliomas with PTEN-mut." (PMID 34336645, 2021). "CLCF1, AEPB1, and OS9 in the PTEN-mut subgroup are the optimal and independent prognostic signatures and can be used as potential targets for the diagnosis, prediction, and treatment of PTEN-mut glioma." (PMID 34336645, 2021). "(+)-JQ1 compound may combine and inhibit the CLCF1, AEBP1, and OS9 interacting proteins, and hence, it can be a potential treatment option for PTEN-mut gliomas." (PMID 34336645, 2021).
liver cancer (3 papers, 2021 to 2024). An epithelial or non-epithelial malignant neoplasm that arises from the liver. "Within the liver cancer cells' tumor microenvironment, the cancer-associated fibroblasts (CAFs)-derived cardiotrophin-like cytokine factor 1 (CLCF1) increases TGF-β secretion in tumor cells." (PMID 38818471, 2024). "This, in turn, activates Erk 1/2 signaling in CAFs, leading to the production of additional CLCF1, creating a positive feedback loop that accelerates the development of liver cancer cells." (PMID 38818471, 2024). "Cardiotrophin-like cytokine factor 1 (CLCF1) is an interleukin-6 (IL-6) family member secreted by cancer-associated fibroblasts (CAFs) that binds to ciliary neurotrophic factor receptor (CNTFR), promoting tumor growth in lung and liver cancer." (PMID 38562778, 2024). "Moreover, CAFs may communicate with liver cancer cells via the cardiotrophin-like cytokine factor 1 (CLCF1)–CXCL6/TGFβ axis, consequently stimulating the development of the stem-cell-like tumor phenotype and the recruitment and polarization of neutrophils, altogether aggravating HCC prognosis." (PMID 35008212, 2021).
Crisponi syndrome (2 papers, 2015 to 2025). "Similar to Crisponi syndrome, which involves variants in CRLF1 or CLCF1 genes, SWS shares overlapping clinical features but has distinct genetic origins." (PMID 41211063, 2025). "Human disease related to inactivation of CLCF-1 leads to autonomic dysfunction in the Crisponi syndrome, also termed cold sweating syndrome." (PMID 26146641, 2015).
osteoporosis (2 papers, 2021 to 2022). A condition of reduced bone mass, with decreased cortical thickness and a decrease in the number and size of the trabeculae of cancellous bone (but normal chemical composition), resulting in increased fracture incidence. "In one study, CLCF1 alleviated bone loss in osteoporosis mouse models by suppressing osteoclast differentiation by activating interferon signalling and suppressing the NF-κB signalling pathway." (PMID 35055176, 2022). "The results suggested that the CLCF1 mRNA levels and log-transformed protein expression were negatively associated with the occurrence of osteoporosis; thus, the lower the CLCF1 mRNA and protein expression levels, the higher the possibility of osteoporosis." (PMID 33430863, 2021). "Nevertheless, this function of CLCF1 in bone remodelling suggests a potentially useful therapeutic role for the treatment of osteoporosis." (PMID 35055176, 2022). "CLCF1 protein levels in the normal and osteopenia groups were higher than those in the osteoporosis group." (PMID 33430863, 2021). "The CLCF1 protein level in the osteoporosis group was significantly lower than that in the normal and osteopenia groups." (PMID 33430863, 2021). "The normal, osteopenia, and osteoporosis groups were assigned values of 0, 1, and 2, respectively, and the relationship between the CLCF1 expression levels and the occurrence of osteoporosis was analyzed using Pearson’s correlation analysis." (PMID 33430863, 2021). "Therefore, further studies are needed to precisely understand the role of CLCF1 in the bone remodelling process and osteoporosis." (PMID 35055176, 2022). "Moreover, the lower the expression levels of CLCF1 mRNA and protein, the higher the possibility of osteoporosis." (PMID 33430863, 2021). "Furthermore, a whole gene chip analysis suggested that the expression levels of CLCF1 in the peripheral blood mononuclear cells (PBMCs) were downregulated in postmenopausal women with osteoporosis." (PMID 33430863, 2021). "Finally, the role of the CLCF1 gene in bone metabolism remains elusive although the results suggest that higher expression levels of the CLCF1 gene in PBMCs are accompanied by higher BMD and a lower incidence of osteoporosis." (PMID 33430863, 2021).
Splenomegaly (2 papers, 2019 to 2022). Abnormal increased size of the spleen. "CLCF1 overexpression in mice leads to splenomegaly, whereas mice heterozygous for CLCF1 display lower circulating leukocyte counts." (PMID 35055176, 2022). "Of note, CLCF1 overexpression in mice leads to splenomegaly, whereas mice heterozygous for CLCF1 display lower circulating leukocyte counts." (PMID 31552057, 2019).
Stroke (2 papers, 2022 to 2024). Sudden impairment of blood flow to a part of the brain due to occlusion or rupture of an artery to the brain. "Stroke was also the main effect in increasing the anti-inflammatory A2 astrocyte markers: Cd14 and Clcf1, whereas Tgm1 was only increased in HT + Stroke vs HT + Sham (P < 0.05)." (PMID 38886874, 2024). "In contrast, stroke-induced genes (Clcf1, Tgm1, S100a10) showed a transient increase at 3 days that was reduced by 7 days." (PMID 35350551, 2022).
Autoimmunity (1 paper, 2019). The occurrence of an immune reaction against the organism's own cells or tissues. "In mice, CLCF1 induces B-cell expansion, enhances humoral responses and triggers autoimmunity." (PMID 31552057, 2019).
coronary heart disease (1 paper, 2021). "Due to differences in the distribution of diseases such as gastrointestinal diseases and hypertension among different groups, we further analyzed the influence of gastrointestinal diseases, hypertension, and coronary heart disease on the expression levels of CLCF1 mRNA and protein in PBMCs." (PMID 33430863, 2021).
fatty liver (1 paper, 2024). "Among these genes, several have been previously linked to the development of fatty liver, including Acaca, Fasn, Pparγ, Cidea, cardiotrophin-like cytokine factor 1 (Clcf1), and Acly." (PMID 39873004, 2024).
glaucoma (1 paper, 2023). Increased pressure in the eyeball due to obstruction of the outflow of aqueous humor. "For each of the 4 clusters, notable genes associated with glaucoma, neuroinflammation, or reactive astrocytes were: Cluster 1 (Nrf2, Hspb1, S100β), Cluster 2 (Ptgs2, Clcf1), and Cluster 4 (C2, Tlr4, Lcn2, H2-T23, Thbs1, Il6ra)." (PMID 37759301, 2023).